BRCA1 (BRCA1 DNA repair associated)
Diseases named in the same sentence as BRCA1 in open-access papers (continued):
Sharing a sentence is not in itself a finding about the gene and the disease.
breast cancer (continued). "In turn, the BRCA1 protein promoted ESR1-gene activation, leading to an increased expression of ER-alpha mRNA and ER protein in breast cancer cell lines." (PMID 39329990, 2024). "There were few differences between BRCA1 and BRCA2 as KRT6B, a breast cancer stem cell marker, is upregulated in LASP cells of BRCA1 mutation carriers compared with others." (PMID 38059556, 2024). "BRCA1 and BRCA2 genes transheterozygosity is rare in the general population but is found to have a similar probability of developing breast cancer, ovarian cancer, or both cancers as compared to single mutations." (PMID 38903278, 2024). "In Thailand, the universal reimbursement of germline BRCA1 and BRCA2 genetic testing for breast cancer patients has been approved since 2022." (PMID 38355628, 2024). "In tamoxifen-resistant breast cancer, the activated PI3K/AKT pathway is responsible for BRCA1 upregulation." (PMID 38977680, 2024). "Resveratrol has demonstrated its ability to regulate BRCA1 gene expression in breast cancer cells, and previous studies have established the binding of MBD proteins to BRCA1 gene promoter regions." (PMID 38711004, 2024). "The same authors reported significant tumor growth inhibition of ART812 when given orally as monotherapy (100 mg/kg QD) in a rat BRCA1‒/‒ and SHLD2‒/‒ breast cancer xenograft model." (PMID 39492835, 2024). "Our data indicate that BRCA1 and MGMT epimutations significantly contribute to the development of breast cancer and ovarian cancer in Saudi cancer patients." (PMID 38542081, 2024). "Hypoxia can modulate breast cancer progression by inhibiting methylation of H3K4, increasing H3K9 methylation and decreasing H3K9 acetylation in the promoter of the BRCA1 gene." (PMID 39282472, 2024). "We next focus on the gene modules of BRCA1 and BRCA2, which are the most commonly encountered genes in breast cancer." (PMID 39013885, 2024). "Notably, BRCA1 mutations are most common in the RING domain, exons 11-13, and the BRCT domain, suggesting that mutations in these domains may play a role in increasing breast cancer risk." (PMID 38543119, 2024). "The aimed to evaluate the impact of MBD proteins on the regulation of BRCA1, BRCA2, and p16 genes and their consequential effects on breast cancer cells." (PMID 38711004, 2024). "In this study, we aimed to determine the roles of constitutional BRCA1 promoter methylation and MGMT promoter methylation in the incidence of breast cancer in Saudi women." (PMID 38542081, 2024). "The incidence of HRD in germline RAD51C/D was lower than in germline BRCA1/2 or PALB2, especially among breast cancer samples." (PMID 38648056, 2024). "This is expected, given that HRDetect was trained on genomes from patients with BRCA1/BRCA2 LOF in breast cancer, whereas NBN plays a role further upstream of BRCA1/BRCA2 in the repair of DNA double-strand breaks." (PMID 38561473, 2024). "In this case study, we use SL-Miner to prioritize potential SL interactions between BRCA1 and DDR-related genes in breast cancer." (PMID 38244572, 2024). "Regarding the genetic mutations that are known to increase the risk of developing BC, the European Society of Breast Cancer Specialists (EUSOMA) estimates that 3% of all BC cases are caused by an underlying deleterious mutation of the BRCA1 or BRCA2 genes." (PMID 39126074, 2024). "Furthermore, the added benefits of breast cancer prevention and surveillance strategies personalized in accordance with carrier status for moderate penetrance genes are less clear than those of the strategies for high-penetrance genes, such as BRCA1 and BRCA26." (PMID 38491043, 2024). "AURKA can also interact and phosphorylate BRCA1 and BRCA2 genes, which are known to promote breast cancer when deregulated." (PMID 38886738, 2024). "Consistent with our assumption, we observed decreased USP4 expression in 63% of the breast cancer tissues, and a positive correlation between USP4 and BRCA1 was found." (PMID 38734703, 2024).
breast cancer (continued). "Using the well-known breast cancer suppressor genes BRCA1 and BRCA2 as examples, in 1,118 breast cancer samples, both genes are fitted with log-norm distributions." (PMID 39541191, 2024). "The expectation is that therapeutic strategies based on PARP inhibition will prove effective in treating ovarian cancer, as well as breast cancer, characterized by the loss of BRCA1/2 function, irrespective of whether the tumors are familial or sporadic in nature." (PMID 38391958, 2024). "Almost all these symptoms are unavoidable in the majority of cases; in fact, many women with BRCA1/2 PV cannot take HRT, for a previous history of breast cancer." (PMID 39624976, 2024). "In this study, we investigated the interplay between WWOX and BRCA1, both frequently inactivated in TNBC, on mammary tumor development and on DNA double-strand break (DSB) repair choice." (PMID 38499540, 2024). "Poor contralateral breast cancer (CBC)-free survival and a prevalence of 14.5% in TNBC patients aged ≤ 60 years were observed, contributing to the update in BRCA1/2 genetic testing guidelines in Korea16." (PMID 38689097, 2024). "We compared our findings to breast (n = 3) and non-breast cancers (n = 25) from individuals heterozygous for CHEK2 gPVs and to breast (n = 7) and non-breast cancers (n = 21) from individuals heterozygous for BRCA1/2 gPVs." (PMID 38848470, 2024). "These intricate genetic variations highlight the complexity of HRD status in breast cancer and the importance of comprehensive testing for HRD beyond just BRCA1 and BRCA2." (PMID 38822929, 2024). "To determine if the difference in these Wnt signaling genes can also be observed in other cancer types, we utilized a publicly available gene expression dataset for 4T1 BRCA1-null and 4T1 BRCA2-null mouse breast cancer cells." (PMID 39028933, 2024). "BRCA1, MYC and IL-6 were identified as the top three hub genes in infected-breast cancer cells based on the connectivity of PPI analysis." (PMID 38654350, 2024). "On molecular level, it was reported that the BRCA1 interacts with the estrogen receptor alpha, which then inactivates estrogen-induced VEGF transcription in breast cancer cells." (PMID 38332226, 2024). "Cumulative lifetime penetrance estimates for female breast cancer are taken from the literature review performed by the All Syndromes Known to Man Evaluator28–32: 0.35 (ATM), 0.73 (BRCA1), 0.72 (BRCA2), 0.19 (CHEK2), and 0.38 (PALB2)." (PMID 38760335, 2024). "Pluripotency markers OCT4, SOX2 with cancer markers BRCA1, BRCA2, ER, PR and HER2 in breast cancer iPSCs; Tal2, EGF, ILF3, UBI2I, BRCA1 and BRCA2 in ovarian cancer iPSCs were analyzed." (PMID 37479967, 2023). "Our primary endpoint was to assess and compare the differences in ultrasonographic features between BRCA1 and BRCA2 breast cancers." (PMID 36905492, 2023).
breast cancer (continued). "This study aimed to assess and compare the ultrasound findings and pathologic features of BRCA1 and BRCA2 breast cancers." (PMID 36905492, 2023). "Next-generation sequencing has led to the identification of prominent genes such as BRCA1 and BRCA2 involved in breast cancer initiation and progression." (PMID 37662839, 2023). "Due to the relevance of BRCA1 as a tumor suppressor in basal-like breast cancers (BLBCs) and considering that these tumors are also characterized by high levels of TAZ activity, we focused on BRCA1." (PMID 37887275, 2023). "Including PALB2 in the routine molecular genetic testing of breast cancer patients is recommended because it is associated with high cancer risk, and preventive and screening programs in PALB2 carriers may improve their life expectancy similarly to BRCA1/2 carriers." (PMID 37686625, 2023). "In contrast, the most common type of BRCA2 breast cancer was luminal-type breast cancer, and the luminal-HER2 type was more frequent in BRCA2 than BRCA1 tumors (p < 0.001)." (PMID 36905492, 2023). "The control group of breast cancer patients certainly contains an unknown number of genetic variants of cancer genes and, therefore, probably, no such good separation is possible as in the healthy and the non-oncological BRCA1/2 cohort." (PMID 37623237, 2023). "Currently, limited studies have addressed the gene–gene interaction among BRCA1, BRCA, and PALB2 in real-world settings of large-scale breast cancer gene analysis." (PMID 38098088, 2023). "However, the development of breast cancer responds to multiple factors and not uniquely to the mitogenic activity of female hormones able to induce genomic instability that drives cancer development, as seen in BRCA1 and BRCA2 mutations." (PMID 38067328, 2023). "BRCA1 plays a crucial role in repairing and recovering DNA damage induced by COH29 in breast cancer cells." (PMID 38124207, 2023). "Tumor tissue derived organoids and snap frozen tissues were analyzed for BRCA1, BRCA2, ER, PR and HER2 in breast cancer, Tal2, EGF, ILF3, UBI2I, BRCA1 and BRCA2 in ovarian cancer." (PMID 37479967, 2023). "Approximately 55%-65% of individuals with BRCA1 and about 45% of females with BRCA2 will develop breast cancer by the age of 70." (PMID 37113463, 2023). "Distinct from liposome mediated gene delivery, in our study we used inorganic CA nano vector for delivering the BRCA1 and BRCA2 genes into three different types of breast cancer cell lines." (PMID 36631481, 2023). "It has been reported that decreased expression of BRCA1 triggers genome-wide EZH2 retargeting and elevates H3K27me3 levels which blocks embryonic cell differentiation and enhances breast cancer migration and invasion." (PMID 37325482, 2023). "On the other hand, we demonstrated, for the first time, a decrease of 40% and 55% in the circRNA/mRNA ratio for BRCA1 and BRCA2, respectively, in breast cancer tissues compared to normal adjacent tissues." (PMID 37046838, 2023). "Our data suggest that TP63, YWHAZ, BRCA1, CCND2, YWHAG, and HIPK2 can be potential genetic markers of prognostic assessment, immune infiltration and chemotherapeutic drug sensitivity in breast cancer patients." (PMID 36673982, 2023). "The current analysis aims to evaluate the prevalence of genetic alterations specific to BRCA1, BRCA2, and PALB2 in a large cohort of Taiwanese breast cancer patients through tumor-targeted sequencing." (PMID 38098088, 2023). "PRMT5 expression was moderately to strongly correlated (Pearson score ≥ 0.4) with established DDR genes such as BRCA1, BRCA2, RAD51, RAD51D, RAD51AP1, FANCA, and FANCI across 125 ovarian and breast cancer cell lines." (PMID 37861290, 2023).
breast cancer (continued). "There was also hypermethylation of several important tumor suppressor genes, including high-penetrance (BRCA1) and moderate-penetrance (PALB2) breast cancer genes." (PMID 38131903, 2023). "Finally, we applied this BRCA1-specific and the previously published BRCA2-specific models to predict the pathogenicity of variants of uncertain significance that were identified in patients with breast cancer by the Qatari National Center of Cancer Care and Research." (PMID 37335020, 2023). "Fifty percent of BRCA1/2 positive women in our study had not undergone annual imaging-based surveillance by mammography or MRI, and none had undergone annual dual screening with mammography and MRI, indicating inadequate breast cancer surveillance in this high-risk group." (PMID 38017478, 2023). "Our study here demonstrated the primary use of biodegradable CA NPs to deliver BRCA1 and BRCA2 plasmids into breast cancer cells and explored the outcome of gene augmentation on tumor regression." (PMID 36631481, 2023). "BRCA1 expression is downregulated through E2F4, and the downregulation of BRCA1 expression increases CSC-like populations in breast cancer cells." (PMID 36833320, 2023). "This work is significant for Black breast cancer patients, who may require CLIA-certified genetic testing because it employs comprehensive sequencing to identify more than the three Ashkenazi Jewish founder variants in BRCA1 and BRCA2 assessed by some DTC genetic tests." (PMID 37775604, 2023). "The frequency of BRCA1 and BRCA2 deletions in breast cancer is higher than the frequency of amplifications and often represents about 10–15% of cases." (PMID 37628606, 2023). "Regarding VUS, we found that 6.99% (10/143) of breast cancer patients and 7.33% (28/382) of ovarian cancer patients were carriers of a VUS in BRCA1/2." (PMID 37664050, 2023). "Poly (ADP‐ribose) polymerase (PARP) inhibitors of BRCA1/2 and ATM, such as Olaparib, have been approved by US FDA for breast cancer and ovarian cancer treatment." (PMID 36653904, 2023). "The study of 94 familial breast cancers demonstrated RAD21 overexpression in 43%, 44% and 33% of BRCA1, BRCA2 and BRCAX tumours, respectively, and expression was associated with shortened cancer-specific overall survival (Hazards Ratio 1.66, p = 0.003)." (PMID 36831687, 2023). "In a previous study, we demonstrated that AZD2281 (olaparib) inhibits cell viability and induces autophagy/mitophagy in BRCA1- and BRCA2-mutant breast cancer cell lines." (PMID 37509303, 2023). "In BRCA1 or BRCA2 mutants, these errors result in chromosomal rearrangements and shifts that are characteristic of hereditary breast cancer." (PMID 37241036, 2023). "The American Society of Breast Surgeons recommends that genetic testing for BRCA1/2 and PALB2 be made available to every women with a personal history of breast cancer." (PMID 37084156, 2023). "We designed our study to deliver BRCA1 and BRCA2 tumor suppressors in the form of plasmid by means of inorganic Carbonate Apatite (CA) nanoparticles (NPs) carrier and evaluated breast cancer cell growth both in vitro and in vivo." (PMID 36631481, 2023).
breast cancer (continued). "Therefore our aim was to develop a BRCA1-specific machine learning model to predict the pathogenicity of all types of BRCA1 variants and to apply this model and our previous BRCA2-specific model to assess BRCA variants of uncertain significance (VUS) among Qatari patients with breast cancer." (PMID 37335020, 2023). "PN2 has a homozygous missense mutation (p.R1028C) predicted to be ‘likely benign’ and has no congenital abnormalities – although chronic lymphocytic leukaemia and breast cancer were reported, suggesting a possible HBOC (BRCA1) phenotype." (PMID 38146508, 2023). "Based on the data gathered, we propose, for the first time, that SOC therapies used in ER+ breast cancer reduce the expressions of DNA repair proteins, XRCC1, FEN1, BRCA1, BRCA2 and RAD51, caretakers in maintaining genomic integrity." (PMID 37914699, 2023). "Transgene expression of BRCA1 and BRCA2 in breast cancer cell lines using the novel vector of CA NPs potentially provided new insight for breast cancer gene therapy." (PMID 36631481, 2023). "Studies have shown that, when comparing Luminal type breast cancer to TNBC, BRCA1 is equally downregulated in mRNA expression for Luminal type and TNBC." (PMID 38137912, 2023). "BRCA1 showed a higher mutation rate in HR− /HER2-zero breast cancer than that in HR−/HER2-low tumors, but without significant difference in both databases, which might suggest that HR−/HER2-zero breast cancer might be a more typical TNBC subtype than HR−/HER2-low tumors." (PMID 37264417, 2023). "In this study, we focused on BRCA1 and BRCA2 gene delivery with a view to reduce breast cancer cell proliferation in different breast cancer cells." (PMID 36631481, 2023). "A study from Saudi Arabia observed that epimutations on BRCA1 and MGMT genes (both genes have been related to breast cancer) can be transmitted from mothers to female newborns, which could potentially transmit breast cancer risk from mothers to their daughters." (PMID 36966332, 2023). "SERS has also been used to target HER2 on breast cancer cells and to identify other cancer markers such as PSA, BRCA1, EGFR, and others." (PMID 37232918, 2023). "In contrast, among breast cancers with HER2 overexpression or ER levels of ≥ 10%, constitutional BRCA1 tumor methylation was a rare event." (PMID 38053165, 2023). "BRCA1 and BRCA2 are detected in at least 5% of unselected patients with breast cancer and in approximately 30% of patients with a positive family history of breast or ovarian cancer." (PMID 37644384, 2023). "In MCF-7 cells, we also found that successful expression of BRCA1 and BRCA2 lowered expression of P-MAPK in the MAPK signaling and controlled breast cancer cell proliferation." (PMID 36631481, 2023). "In women, the degree of tumoral differentiation may result from the interaction of GATA-3 with the BRCA1 gene, which cause the formation of protein complexes that suppress genes associated with the triple negative basal-like phenotype (ER−, PR−, HER-2−, and CK 5/6+ or CK14+) in breast carcinomas." (PMID 37483298, 2023). "BRCA1 compared to BRCA2 result was only a trend, most likely due to the low number of breast cancer incidences." (PMID 35469032, 2022). "In general, the prevalence and spectrum of the BRCA1 and BRCA2 genes in the Hakka patients with breast cancer and ovarian cancer from southern China are different from those in other ethnic groups." (PMID 35918668, 2022).